INS (insulin)
Diseases named in the same sentence as INS in open-access papers (continued):
Sharing a sentence is not in itself a finding about the gene and the disease.
diabetes (continued). "Hyperglycemia, insulin resistance, and dysfunction of insulin secretion are major characteristic features of type 2 diabetes mellitus." (PMID 30538754, 2018). "The “classic” clinical criteria for MODY diagnosis include onset of diabetes before age of 25 years, insulin-independence and at least two-generational family history of diabetes." (PMID 29666556, 2018). "In fact, mice overexpressing Lin28a and Lin28b show an insulin-sensitized state, with protection against high-fat diet induced diabetes." (PMID 30034366, 2018). "Defects in pancreatic insulin secretion and/or defects in insulin action result in DT2 (constituting 90% of all diabetes cases)." (PMID 30026880, 2018). "The average duration of diabetes was 10.31 years, and 91.34% of patients received insulin therapy or anti-diabetic medication." (PMID 29291738, 2018). "This provides evidence for mitochondrial dysfunction under conditions of insulin resistance even before the onset of diabetes." (PMID 30443826, 2018). "In contrast, diabetes duration was positively related to insulin requirement and HbA1c levels (p < 0.05)." (PMID 30250851, 2018). "Currently available medications for the treatment of diabetes are divided into four categories: insulin, insulin secretagogues, insulin sensitizers, and prandial glucose regulators." (PMID 30524480, 2018). "Long-term high blood sugar and oxidative damage reduce islet β-cell synthesis and secretion of insulin, and reduce the number of islet β cells; both of which increase the development of diabetes." (PMID 30202421, 2018). "Intensive insulin therapy (IIT; 4–7 mmol/L) is the preferred treatment for type 1 diabetes mellitus (T1DM) patients to reduce the risk of cardiovascular disease (CVD)." (PMID 30116746, 2018). "The study found that due to biological regulation dysfunction of insulin, diabetes patients commonly accompanied by lipid metabolism disorder and were complicated by hyperlipidemia." (PMID 29739462, 2018). "One important obstacle to addressing this issue is that most studies investigate the animal models or patients with diabetes or obesity, which is unable to exclude the involvement of insulin action." (PMID 30275974, 2018). "Diabetes mellitus is a chronic, progressive disorder that results from the body’s inability to either produce sufficient insulin or utilize it efficiently." (PMID 29770126, 2018). "Glucose and insulin also modulate LAT1 expression: increase of glucose in diabetes induces a down-regulation of LAT1 expression with consequent sarcopenia in diabetes patients." (PMID 29988369, 2018). "Insulin levels in the blood were determined to further characterize the model of experimental diabetes and subcutaneous insulin treatment." (PMID 30426021, 2018). "Approximately 34.6% of patients with diabetes report that they miss applying insulin at least once a month." (PMID 29791677, 2018). "Ethnic differences in the pathophysiological mechanisms of diabetes, such as the degree of obesity, the insulin secretion capacity, and insulin resistance, have been documented between Japanese and Western participants." (PMID 29615971, 2018). "The guideline recommends intensive diabetes therapy in T1DM with basal-bolus (basal prandial) regimens that mimic the normal β-cell insulin secretion." (PMID 29508275, 2018). "In the present study, insulin levels were similar in prediabetes and diabetes and in two groups with different duration of disease." (PMID 30185190, 2018). "Individuals with diabetes are unable to make a hormone called insulin – which normally stimulates certain cells to absorb sugar from the blood – or their cells are less able to respond to this hormone." (PMID 30520733, 2018). "Although there are some studies that have attempted to relate diabetes/insulin to autism, the evidence is limited." (PMID 29791472, 2018). "Using our insulin infusion protocol, the steady-state plasma insulin level was previously reported to be 1200 pmol/L in patients with type 2 diabetes mellitus." (PMID 29791512, 2018).
diabetes (continued). "As the top two representative drugs of insulin-sensitizers, TZDs and metformin are widely applied in clinics for diabetes." (PMID 29552319, 2018). "Maternal diabetes was well controlled with diet (n = 4), insulin (n = 6) or glyburide (n = 7), as evidenced by an average HgbA1c approaching that of controls." (PMID 29470513, 2018). "Mini games about food and intake of insulin were seen as more useful for children recently diagnosed with diabetes." (PMID 29385750, 2018). "There were more females as well as a higher rate of Congestive heart failure [CHF], unstable angina, insulin-treated diabetes, diabetes with end organ damage (DM+EOD) and neurologic dysfunction (ND) in the SITA group." (PMID 30102699, 2018). "For example, insulin hydrogel used for the treatment of diabetes responds to the glucose to initiate the release of insulin." (PMID 29346275, 2018). "Patients with diabetes duration above the median value, < 9 years of school education, and those being treated with insulin or ≥ 3 oral antidiabetic drugs at baseline were found to be less likely to reach their assigned HbA1c level." (PMID 29357854, 2018). "longum can delay the onset of STZ-induced diabetes, possibly via its effect on the insulin signalling pathway." (PMID 30662733, 2018). "The history of the steps leading to the discovery of insulin overlaps, at least partially, with the history of diabetes and of pancreatic anatomy." (PMID 30405529, 2018). "There was a significant decrease (p < 0.05) in body weight and serum insulin level whereas an increase in serum glucose level of vehicle control rats after induction of diabetes by intraperitoneal administration of STZ." (PMID 29805347, 2018). "First, individuals with diabetes were excluded because the vast majority of these patients receive diabetes treatments that can alter insulin sensitivity and HOMA-IR values." (PMID 30509229, 2018). "The most common treatment (77.9%) for T1DM was both short and long-acting insulin analogues, used alone or in combination with other treatments, while oral anti-diabetes drugs combined with insulin was the most frequent option (60.4%) for T2DM." (PMID 30479669, 2018). "The proband’s mother had developed diabetes at age 23, and was treated with oral hypoglycaemic agents and eventually insulin." (PMID 29764441, 2018). "Exercise improves skeletal muscle insulin sensitivity, making exercise an efficacious treatment for type 2 diabetes mellitus and numerous other chronic conditions." (PMID 30013070, 2018). "Most treatments for diabetes involve replacing the lost insulin or boosting the hormone’s activity in the body." (PMID 30520733, 2018). "We used 40-day-old BioBreeding (BB) DRLyp/Lyp rats (a model of spontaneous autoimmune type 1 diabetes) and diabetes-resistant DRLyp/+ and DR+/+ littermates (controls) to investigate beta cell function in vivo, and insulin and glucagon secretion in vitro." (PMID 29209740, 2018). "Our data show the human GLP-1 analogue liraglutide ameliorates beta-cell function and insulin secretion capacity compared with 8-week metformin treatment in young patients with new-onset type 2 diabetes mellitus." (PMID 30564288, 2018). "Insulin resistance and impaired insulin secretion are the core pathophysiologic defects in type 2 diabetes mellitus (T2DM)." (PMID 29791512, 2018). "These patients were obese and had a family history of diabetes, preserved insulin secretion, low prevalence of beta cell autoimmunity, and the ability to discontinue insulin therapy." (PMID 30526658, 2018). "In patients with autoimmune thyroid disease, the presence of GAD Ab was shown to be consistent with the onset of diabetes, lower body mass index, higher hemoglobin A1c level, and higher frequency of insulin therapy at a younger age." (PMID 30013597, 2018). "Quality of Life (QoL) of insulin-naïve people with type 2 diabetes mellitus (T2DM) improves after transition to insulin." (PMID 28803366, 2018).
diabetes (continued). "Rats were randomly divided into five groups: control (C), diabetes (D), diabetes with insulin (I), diabetes with pravastatin (P), and diabetes with insulin and pravastatin (IP)." (PMID 29682576, 2018). "Fear of hypoglycemia can adversely affect diabetes management and clinical outcomes through reduced adherence to medications or a reluctance of physicians to titrate insulin more aggressively." (PMID 29549574, 2018). "For example, in the Diabetes MILES – Australia study half of participants with type 2 diabetes using insulin believed that taking insulin meant their diabetes had become worse and that insulin caused weight gain." (PMID 29347915, 2018). "According to results, similar to gene expression levels, the insulin signaling pathway-related proteins were significantly upregulated by diabetes." (PMID 30602713, 2018). "On applying the Diagnostic and Statistical Manual of Mental Disorders, 10%–15% of girls with diabetes meet the criteria for subclinical eating disorders including binge eating and insulin underdosing for weight control." (PMID 29682577, 2018). "Functional foods containing peptides offer the possibility to modulate the absorption of sugars and insulin levels to prevent diabetes." (PMID 30249015, 2018). "Insulin, insulin resistance and Vicorder pulse wave velocity was greater in diabetes (p < 0.01), as was diastolic blood pressure (p < 0.04)." (PMID 29483674, 2018). "An example of decision support software is the Bolus Wizard or bolus calculator, which advises people with diabetes on meal insulin dose." (PMID 30470680, 2018). "Lawrence was himself diagnosed with diabetes prior to the invention of insulin therapy, and suffered quite severely before early access to insulin saved his life." (PMID 29514263, 2018). "Growth of publications in diabetes depression/suicide started in 1949 with an article published in The New England Journal of Medicine about the effects of a large dose of insulin taken for suicidal attempt." (PMID 30386407, 2018). "The mean reimbursement of insulin-treated patients was €12,200 versus €5200 for other people with diabetes." (PMID 28190188, 2018). "The protein tyrosine phosphatase1B (PTP1B) is a negative regulator of both insulin and leptin signaling, and shows a highly validated therapeutic target for the treatment of diabetes and obesity." (PMID 29593573, 2018). "Diabetes mellitus is a metabolic disease in which the body is unable to produce insulin or respond to insulin production, consequently leading to abnormal metabolism of carbohydrates, lipids and proteins causing elevation of glucose in the blood." (PMID 30522526, 2018). "Most patients suffer from type-2 diabetes, which is initiated by insulin resistance in muscle and adipose tissue often beginning years before diabetes is diagnosed." (PMID 29731775, 2018). "Questions related to participants’ practices to control and manage their diabetes were as follows: 15.9% were on insulin therapy, and 89.4% with oral hypoglycemic agents, 59.9% were using also a special diet therapy." (PMID 29678148, 2018). "C-peptide is the best measure of endogenous insulin secretion and is widely used in the clinical management of patients with diabetes." (PMID 29401509, 2018). "Diabetes mellitus (DM) is a group of diseases characterized by hyperglycemia resulting from absolute insulin deficiency (type 1 DM) or insulin resistance, together with a relative insulin secretion defect (type 2 DM)." (PMID 29710851, 2018). "Within the first treatment year there was furthermore a tendency towards a lower proportion of insulin analogues used as basal insulin supplementation in CHI patients with diabetes (20% vs. 26% in patients with T1DM, p = 0.8)." (PMID 30577875, 2018). "Several isolated computational models of diabetes-related biological systems and processes such as macronutrient metabolism, macronutrient energy balance, insulin response, and insulin resistance have been developed previously." (PMID 29444133, 2018).
diabetes (continued). "While insulin therapy was traditionally managed by specialist diabetes services it is now largely managed in primary care by Practice Nurses (PNs) and General Practitioners (GPs)." (PMID 29788908, 2018). "The magnitude of this β cell stress from mutant insulin species dictates the outcome of severe/early-onset or mild/late-onset diabetes." (PMID 29864031, 2018). "We defined incident cases of pharmacologically treated type 2 diabetes as having the first occurrence of diabetes diagnosis in primary or specialist care and one or more prescriptions of non-insulin glucose-lowering drugs within 6 months of diagnosis." (PMID 29995214, 2018). "In other cases, children described how close friends often became very aware of their diabetes‐related routines and, at specific times, would prompt them to undertake tasks such as blood glucose self‐monitoring or administering insulin." (PMID 29961962, 2018). "Insulin therapy has been widely used to treat and maintain glycaemic control, and to help reduce both macro-and-microvascular complaints." (PMID 30417151, 2018). "In our population, one important characteristic was that the average duration of diabetes was almost twenty years; however, the mean number of years on insulin therapy was only six, suggesting a significant delay for commencing insulin." (PMID 30116737, 2018). "Majority of the patients were on 2 drugs for the control of diabetes (55.2%, n = 91), and the most common drug used was metformin (81.8%, n = 135), followed by gliclazide (38.2%, n = 63), and insulin (33.9%, n = 56)." (PMID 29951554, 2018). "Such patients will develop brittle diabetes as they require exogenous insulin after surgery and in the apancreatic state lose counter-regulatory homeostatic mechanisms (i.e., glucagon)." (PMID 30788460, 2018). "A study among Chinese with normal glucose tolerance also showed that participants with a family history of diabetes had poorer insulin sensitivity and greater insulin resistance than those without a family history." (PMID 30544761, 2018). "Conversely, the effects of Xen on GIP-mediated insulin and glucagon release were greatest in humans with impaired glucose tolerance but blunted in those with mild type 2 diabetes mellitus." (PMID 29466430, 2018). "This method can be used for any patient with diabetes in combination with the use of varying doses of rapid-acting insulin or continuous subcutaneous insulin infusion." (PMID 29791661, 2018). "We compared the effects of insulin lispro mix 25 (LM25) and insulin lispro mix 50 (LM50) on postprandial glucose excursion in patients with type 2 diabetes mellitus (T2DM)." (PMID 29520742, 2018). "In pre-diabetes period, the whole body insulin sensitivity of GK rats increased significantly when compared to Wistar rats but the rats became insulin resistance at 8 weeks." (PMID 30687391, 2018). "Knockout of miR-7 in adult islet β cells in vivo leads to defects in insulin secretion and diabetes." (PMID 30290306, 2018). "We recently developed conditions for culturing podocytes which mimic those experienced by podocytes during diabetes, an environment rich in glucose, insulin and inflammatory cytokines, TNFα and IL-6, which promotes insulin resistance." (PMID 29500363, 2018). "Women, on the other hand, need to attain higher levels of BMI to reach the same levels of visceral and ectopic fat required to become insulin resistant and so to develop diabetes." (PMID 29671082, 2018). "Risk of dementia was assessed by Cox proportional hazard regression with adjustment for insulin, glucose, and other covariates and, in a second model, after censoring for incident cases of diabetes mellitus." (PMID 29997193, 2018). "Insulin sensibility in mice with diabetes was improved upon the administration of methylswertianin and bellidifolin phytochemicals." (PMID 29382104, 2018).
diabetes (continued). "In this cohort, Indigenous Australians were more likely to have insulin-treated diabetes, which is reflective of the greater severity of diabetes in this population." (PMID 29769031, 2018). "As key frontline healthcare professionals, nurses are responsible for proper insulin administration for hospitalized patients with diabetes." (PMID 30155295, 2018). "‘all of a sudden they get diabetes, and they say you’ve got to have insulin, then they say you’ve got to exercise to reduce your insulin." (PMID 29371269, 2018). "This study is aimed to study the changes of emotional behaviors and memory performances, glucose metabolism, and brain insulin signaling in rats with diabetes subjected to CUMS." (PMID 30622594, 2018). "These include insulin injections and blood glucose [BG] self-measurements to keep their BG within the desired range, i.e. HbA1c below 53 to 58 mmol/mol, if insulin reactions and diabetes-related complications are to be avoided." (PMID 29529063, 2018). "Genetic defects in the pancreatic β-cells result in the decrease of insulin production required for glucose utilization thereby lead to early-onset diabetes (often <25 years)." (PMID 29867778, 2018). "Because many insulin-treated diabetes patients are below the age at which breast cancer is usually diagnosed, and given the long latency of breast cancer, MD serves as an attractive intermediate endpoint for identifying potential carcinogenic effects." (PMID 30092829, 2018). "Il18−/− mice show dyslipidemia at 6 weeks old, develop diabetes mellitus, and show high glucose and insulin levels and arteriosclerosis at 6 months old, and NAFLD or NASH at 48 weeks old." (PMID 29514661, 2018). "Attempts to control glucostasis have largely been driven by the goal of engineering an artificial pancreas and managing its insulin delivery to aid with the management of type 1 diabetes mellitus." (PMID 29367240, 2018). "Thiamine therapy improved diabetes control in more than 70% of participants (11/15) with four individuals managing to stop insulin treatment." (PMID 29450569, 2018). "Insulin signaling in brain plays an important role in the development and progression of diabetes mellitus, as well as diabetic encephalopathy." (PMID 30622594, 2018). "The therapeutic strategies used to treat diabetes mainly focus on reducing and controlling blood glucose and recovering insulin level." (PMID 30337946, 2018). "Impaired insulin secretion in the presence of insulin resistance is the key feature of type 2 diabetes mellitus (T2DM)." (PMID 29511288, 2018). "Due to a progressive decline in beta-cell function, a considerable number of patients with type 2 diabetes mellitus (T2D) ultimately require multiple daily injections of large doses of insulin for glycemic control." (PMID 30410846, 2018). "Residual secretory capacity and enhanced peripheral insulin sensitivity probably account for low insulin requirements of CHI patients with diabetes." (PMID 30577875, 2018). "Most diabetes cases are classified as type 2 diabetes mellitus (T2DM), which shows progressive loss of insulin secretion on the background of insulin resistance." (PMID 29420588, 2018). "Diabetes is a metabolic disease, characterized by chronic hyperglycemia resulting from the body's inability to produce and/or use insulin." (PMID 30363935, 2018). "Two main features of Type 2 diabetes mellitus is the increased cell resistance to insulin and the dysfunction of the insulin-producing cell in the pancreas (β-cells)." (PMID 30345140, 2018). "Insufficient and/or ineffective insulin secretion or both of them can lead to diabetes mellitus (DM)." (PMID 29808089, 2018). "Patients with CVD were older, had longer diabetes duration, used more insulin, and had a higher level of HbA1c at baseline, as well as lower eGFR levels (data not shown)." (PMID 30071872, 2018).